ATP6V1G2-DDX39B (ATP6V1G2-DDX39B readthrough (NMD candidate))
Gene: Protein-coding gene on chromosome 6 (31,530,219 to 31,546,608, reverse strand). Ensembl gene ENSG00000254870.
Genetic constraint (gnomAD): Missense variants: 47 observed, 79.43 expected, observed/expected ratio (o/e) 0.59, 90% interval 0.47 to 0.75. Synonymous variants: 26 observed, 28.18 expected, observed/expected ratio (o/e) 0.92, 90% interval 0.68 to 1.28.